APELA (apelin receptor early endogenous ligand)
Description:
Peptide hormone that functions as endogenous ligand for the G protein-coupled apelin receptor (APLNR/APJ), that plays a role in the regulation of normal cardiovascular function and fluid homeostasis. Functions as a balanced agonist activating both G(i) protein pathway and beta-arrestin pathway of APLNR. Downstream G proteins activation, apelin can inhibit cAMP production and activate key intracellular effectors such as ERKs. On the other hand, APLNR activation induces beta-arrestin recruitment to the membrane leading to desensitization and internalization of the receptor. Required for mesendodermal differentiation, blood vessels formation and heart morphogenesis during early development and for adult cardiovascular homeostasis. Acts as a motogen by promoting mesendodermal cell migration during gastrulation by binding and activating APLNR. Acts as an early embryonic regulator of cellular movement with a role in migration and development of cardiac progenitor cells. May act as a chemoattractant for the activation of angioblast migration toward the embryonic midline, i.e. the position of the future vessel formation, during vasculogenesis. Positively regulates sinus venosus (SV)-derived endothelial cells migration into the developing heart to promote coronary blood vessel sprouting. Plays a role in placental vascular development; promotes placental trophoblast invasion and spiral artery remodeling in the uterus. Involved in the regulation of maternal cardiovascular homeostasis to prevent gestational hypertension and for potent cardioprotective functions during heart failure. Mediates myocardial contractility in an ERK1/2-dependent manner (By similarity).
Synonyms: ELA; TDL; Ende
Tractability: Antibody: UniProt places it where antibodies can reach, with high confidence; its Gene Ontology location is reachable by antibodies, with high confidence; UniProt predicts a signal peptide or a membrane-spanning region.
Gene: Protein-coding gene on chromosome 4 (164,876,944 to 164,899,007, forward strand). Ensembl gene ENSG00000248329.
Subcellular location: Secreted; Secreted, extracellular space
Gene Ontology:
Molecular function: apelin receptor binding; hormone activity
Biological process: apelin receptor signaling pathway; G protein-coupled receptor signaling pathway; positive regulation of angiogenesis; positive regulation of G protein-coupled receptor internalization; positive regulation of trophoblast cell migration; adult heart development; cell migration involved in mesendoderm migration; coronary vasculature development; embryonic heart tube development; endoderm development; heart development; mesendoderm migration; mesoderm migration involved in gastrulation; placenta blood vessel development; positive regulation of blood vessel endothelial cell proliferation involved in sprouting angiogenesis; positive regulation of ERK1 and ERK2 cascade; positive regulation of heart contraction; vasculogenesis
Cellular component: extracellular region
Homologues: Orthologues: chimpanzee APELA (100% identical), macaque APELA (93% identical).
Diseases named in the same sentence as APELA in open-access papers:
APELA is named in the same sentence as 43 diseases in open-access papers, as found by Europe PMC text mining. Sharing a sentence is not in itself a finding about the gene and the disease. The quoted sentences say what the papers report.
Hypertension (11 papers, 2020 to 2025). The presence of chronic increased pressure in the systemic arterial system. "Apelin has been confirmed to be strongly associated with the occurrence and development of hypertension, and apelin and APELA share the APJ and exhibit a similar cardiovascular profile." (PMID 35630008, 2022).
glioma (4 papers, 2019 to 2022). A benign or malignant brain and spinal cord tumor that arises from glial cells (astrocytes, oligodendrocytes, ependymal cells). "Increased APELA transcription is associated with an increased histological grade of gliomas and poor prognosis of patients with GBM." (PMID 35610201, 2022). "Analysis of APELA and the Apelin receptor gene expression in brain tumor datasets showed that high APELA expression was associated with poor patient survival in both glioma and glioblastoma, and APELA expression correlated with glioma grade." (PMID 30917521, 2019). "To explore the potential role of APELA in glioma, we analyzed microarray data from two different glioma gene expression studies for the relationship between APELA expression and patient survival." (PMID 30917521, 2019). "Moreover, consistent with our findings, increased APELA immunoreactivity was observed in high-grade glioma when compared to that of low-grade glioma using a commercially available anti-APELA antibody." (PMID 30917521, 2019). "Using two independent microarray datasets for glioma (GSE33331 and GSE43289), high APELA expression was associated with poor patient survival (p value < 0.05), both when all grades of glioma were analyzed together and when GBM patients were analyzed independently." (PMID 30917521, 2019). "In addition, APELA expression tended to increase in accord with the histological grade of the glioma." (PMID 30917521, 2019). "In addition, we found that APELA gene expression was significantly overexpressed in RNA isolated from FFPE blocks of GBM patient tissue compared to low-grade glioma tissue and normal brain tissue." (PMID 30917521, 2019). "In addition, our qPCR data on APELA expression on FFPE tissue correlated well with the microarray database analysis, since we found higher APELA expression in GBM than in low-grade glioma." (PMID 30917521, 2019).
preeclampsia (4 papers, 2018 to 2020). Preeclampsia is a hypertensive disorder of pregnancy that is characterized by new-onset hypertension with proteinuria presenting after 20 weeks of gestation, and depending on mild or severe forms may initially present with severe headache, visual disturbances, and hyperreflexia. "It was firstly discovered that APELA knockout pregnant mice exhibited a hypertensive symptom accompanied with proteinuria and glomerular endotheliosis, which were manifested as preeclampsia-like symptoms." (PMID 33240613, 2020). "Summary of studies about the expressional changes of APLN and APELA in the polycystic ovary syndrome (PCOS), Ovarian cancer (OvCa), preeclampsia (PE) and gestational diabetes mellitus (GDM)." (PMID 33240613, 2020).
ovarian carcinoma (3 papers, 2019 to 2020). A malignant neoplasm originating from the surface ovarian epithelium. "Recently, an elevated APELA level was documented in various histotypes of ovarian cancers, especially in ovarian clear cell carcinoma (OCCC)." (PMID 33240613, 2020). "For example, APELA has been found to be overexpressed ovarian cancer, and APELA promoted cell growth and cell cycle progression in ovarian cancer cell lines." (PMID 30917521, 2019).
brain tumor (2 papers, 2019 to 2021). "We found that both APELA mRNA and protein are expressed at high levels in a subset of brain tumor patients, and that APELA is also expressed in putative stem cell niche in GBM tumor tissue." (PMID 30917521, 2019).
brain cancer (1 paper, 2019). A primary or metastatic malignant neoplasm affecting the brain. "In conclusion, we demonstrated that the poorly characterized APELA gene is dysregulated at the mRNA and protein level in brain cancer, and that APELA expression is correlated with pathological tumor grade and poor survival." (PMID 30917521, 2019).
cardiovascular malformations (1 paper, 2019). "In the human adult, APELA expression is mainly restricted to endocrine organs including the kidney and placenta, and has been shown to play an important role in pre-eclampsia and cardiovascular malformations in mice." (PMID 30917521, 2019).
endothelial dysfunction (1 paper, 2022). In vascular diseases, endothelial dysfunction is a systemic pathological state of the endothelium (the inner lining of blood vessels) and can be broadly defined as an imbalance between vasodilating and vasoconstricting substances produced by (or acting on) the endothelium. "APELA deficiency may lead to placental ischemia and maternal kidney/endothelial dysfunction, and contribute to either GH or PE in pregnant women." (PMID 35630008, 2022).
glioblastoma (1 paper, 2019). The most malignant astrocytic tumor (WHO grade IV). "We hypothesize that APELA plays an important but poorly understood role in glioblastoma initiation and/or development." (PMID 30917521, 2019). "Our data suggest that APELA may play an important role in glioblastoma initiation and/or development, and could be a therapeutic target." (PMID 30917521, 2019). "Consequently, APELA may play an important role in glioblastoma tumorigenesis and may be a future therapeutic target." (PMID 30917521, 2019).
Obesity (1 paper, 2023). Accumulation of substantial excess body fat. "Similarly, some DEGs of the COPD dataset, like the regulator of BMPR2 pathway and APELA, are also the obesity-related genes." (PMID 37886639, 2023). "As for patients with COPD, the Activin A Receptor Type 2B (ACVR2B) and Transforming Growth Factor Beta 1 (TGFβ1), which were the key modulators of BMPR2 pathway, were significantly downregulated, as well as the obesity-related gene Apelin Receptor Early Endogenous Ligand (APELA)." (PMID 37886639, 2023).
tumor (3 papers, 2019 to 2025). "Our findings in the BT238 GBM PDX are consistent with the molecular heterogeneity of GBM tumors, since we found a significant variation in APELA expression in BTICs derived from different regions of the same GBM tumor (BT238XY versus BT238Z)." (PMID 30917521, 2019). "Cells that co-expressed Nestin and APELA mRNA were found in discrete regions throughout tumor tissue from three different GBM patients." (PMID 30917521, 2019). "Taken together, our results suggest that APELA is expressed in a stem cell niche within GBM tumor tissue." (PMID 30917521, 2019). "Furthermore, by using RNA-ISH probes, we showed that APELA mRNA was expressed both in GBM tumor tissue and most interestingly in cells that co-express the stem cell marker Nestin." (PMID 30917521, 2019). "Furthermore, using IHC, we found a significant overlap in cells that express both Nestin and APELA in GBM tumor tissue." (PMID 30917521, 2019). "In addition, significantly higher APELA expression was found in BTICs isolated from the central region of a GBM tumor (BT238Z) when compared with BTICs isolated from the tumor periphery (BT238XY)." (PMID 30917521, 2019). "Thus, future studies should focus on the role of APELA in these tumor types and whether APELA may be an important target for therapeutic intervention." (PMID 30917521, 2019). "Thus, similar patterns of Nestin and APELA co-expression were found at the mRNA level (RNA-ISH) and protein level (IHC) in GBM patient tumor specimens." (PMID 30917521, 2019). "APELA was originally considered to be a noncoding transcript, and thus APELA expression data are absent from many of the gene expression databases of brain cancer tumors, such as The Cancer Genome Atlas (TCGA) and REMBRANDT (Repository for Molecular BRAin Neoplasia DaTa)." (PMID 30917521, 2019). "Moreover, when APELA expression from the GSE43289 dataset was analyzed based on the grade of the tumor tissue, although the number of samples analyzed in each group varied, the APELA expression was found to increase with tumor sample grade, with the highest APELA found in GBM (Grade IV)." (PMID 30917521, 2019).
APELA also shares sentences with these, for which no sentence is quoted: cancer (4 papers); heart failure (4); renal disease (3); diabetic kidney disease (2); myocardial infarction (2); renal tumors (2); acute kidney injury (1); benign kidney tumours (1); benign tumours (1); cardiovascular diseases (1); chronic lymphocytic leukaemia (1); clear cell carcinomas (1); clear cell renal cell carcinoma (1); diabetes (1); diabetic retinopathy (1); gestational diabetes mellitus (1); heart diseases (1); intrauterine growth restriction (1); ischaemic cardiomyopathy (1); kidney (1); kidney cancer (1); low grade glioma (1); malignant hypertension (1); malignant thyroid tumours (1); oncocytomas (1); ovarian clear cell cancer (1); Parkinson disease (1); polycystic ovary syndrome (1); pulmonary arterial hypertension (1); renal oncocytomas (1).
A further 2 diseases each share a sentence with APELA in 1 paper.